INS (insulin)
Diseases named in the same sentence as INS in open-access papers (continued):
Sharing a sentence is not in itself a finding about the gene and the disease.
Hypoglycemia (continued). "Rather than increasing the basal insulin dose beyond the suggested ceiling, other glucose-lowering agents should be added to basal insulin in a stepwise manner (if the patient is not already receiving them), depending on the need for weight loss, risk of hypoglycemia, and cost." (PMID 34165382, 2021). "Additionally, carvedilol treatment improved the feeding response to insulin‐induced hypoglycaemia in diabetic animals made ‘hypoglycaemia unaware’ using repeated injections of 2‐deoxyglucose, suggesting the treatment improved awareness of hypoglycaemia as well." (PMID 33855225, 2021). "Parasympathetic activation during insulin-induced hypoglycemia may be also anti-arrhythmic." (PMID 33898141, 2021). "Although insulin supplementation may be appropriate in these individuals to improve glycemic control, it will also increase the risk of hypoglycemia and may not limit glucose variation." (PMID 34879878, 2021). "Also, this action mechanism is insulin-independent; as such it does not increase the risk of hypoglycemia, making it attractive for use in normoglycemic individuals." (PMID 35004776, 2021). "Even with closed-loop glucose-responsive insulin delivery, users usually need to plan for exercise, announcing exercise to the algorithm in advance, and may still require carbohydrate intake to prevent hypoglycaemia." (PMID 33550442, 2021). "However, general insulin therapy cannot prevent severe hypoglycemia and long-term complications." (PMID 33407888, 2021). "The proper insulin injection technique is vital in glycemic control, and the incorrect injection technique may lead to poor absorption, thereby severe outcomes such as hypoglycemia, hypoglycemia, lipohypertrophy, or lipoatrophy." (PMID 34497858, 2021). "We hypothesize that more frequent and severe hypoglycemia can occur shortly after LCD initiation as a result of inadequate lowering of insulin doses as the ones who mentioned hypoglycemia as the reason for LCD termination were the ones who ended with LCD early." (PMID 34836158, 2021). "In addition, acT1ve provides more information on hypoglycemia treatment, pre-exercise and postexercise insulin and carbohydrate advice, and an educational food guide that highlights the importance of low and high glycemic index foods in the context of exercise management." (PMID 34647896, 2021). "In order to elucidate whether SF1 neurons are linked to this effect, an elegant experiment using optogenetic and chemogenetic tools was done by Gregory J Morton and colleagues, showing that selective inhibition of SF1 neurons blocked recovery from insulin-induced hypoglycemia." (PMID 34201257, 2021). "In a prospective randomized controlled trial, the percentage of patients with major hypoglycemia in the insulin aspart group reduced from 11% to 8% in the first and last 3 months of the treatment, while the proportion was unaffected (11%) in the human insulin group." (PMID 34071359, 2021). "Furthermore, reducing insulin did not increase the risk of ketoacidosis or lactatemia and there were no episodes of severe hypoglycaemia." (PMID 33914197, 2021). "Moreover, GhIRKO mice required reduced glucose infusion rates during hyperinsulinemic-hypoglycemic clamps, suggesting that suppressed ghrelin release resulting from direct insulin action on ghrelin cells usually limits ghrelin’s full potential to protect against insulin-induced hypoglycemia." (PMID 34473648, 2021). "This weight increase was not caused by an increase in rapid-acting insulin doses, at least in patients on fixed-dose regimens, but it could be associated with the fear of hypoglycemia, which would justify greater food intake and less physical activity." (PMID 34591409, 2021). "However, when exogenic levels of insulin are to high, hypoglycemia may occur during or after exercise." (PMID 33633280, 2021). "Finally, higher daily insulin dose on AP systems might be just related to underdosing of insulin before entering the studies due to fear of hypoglycemia." (PMID 33819289, 2021).
Hypoglycemia (continued). "Therefore, this study is aimed to evaluate the effectiveness of health education on knowledge about hypoglycemia and insulin pen use among outpatients with T2DM at a primary care hospital in Vietnam and to examine the potential factors influencing this effectiveness." (PMID 34497858, 2021). "Given its greater affordability, patients who are well controlled on NPH may be able to continue on this therapy, since reductions in severe hypoglycemia with newer basal insulin analogs compared with NPH seen in some clinical trials may not be evident in clinical practice." (PMID 34165382, 2021). "Only 3.1% of insulin-treated patients had an investigator-reported adverse event related to hypoglycemia and these patients accounted for only 5 MACE events; however, some hypoglycemic events may not have been reported and may have contributed to a higher rate of MACE in insulin-treated patients." (PMID 34158057, 2021). "Furthermore, insulin delivery strategies using microneedles should be more deeply examined to achieve the accurate and consistent delivery of insulin, since hypoglycemia could result from an overdose." (PMID 33466845, 2021). "Earlier features of glucose responsive insulin delivery systems include the low glucose suspend feature which interrupts insulin delivery below a defined glucose threshold, and predictive low glucose suspend which predicts pending hypoglycaemia and suspends insulin delivery in advance." (PMID 33950566, 2021). "However, inadequate knowledge and malpractice on insulin self-administration could result in poor treatment outcome and insulin-related complications like hypoglycemia." (PMID 33556090, 2021). "Moreover, the unique hypoglycemic mechanism of SGLT2is, which involves an increase in glucosuria and is not insulin-dependent, means that the risk of hypoglycemia is low, which is conducive to lower cardiovascular risk." (PMID 34349651, 2021). "Conceptually, patients using sulfonylureas and insulin may have been at greater risk of hypoglycemia (DPP-4i have negligible hypoglycemia risk); unfortunately, we could not test such hypothesis." (PMID 34857046, 2021). "Similarly, the phenotype of PC2 is reduced growth and chronic hypoglycaemia caused by a lack of glucagon and insulin processing." (PMID 34187565, 2021). "Exercise in patients treated with insulin is associated with an increased risk of hypoglycemia because the concentration of exogenous insulin is not able to drop immediately, as is the case at the beginning of exercise in healthy people with functional beta cells of the pancreas." (PMID 34948667, 2021). "While hypoglycemia and weight gain are well-known side effects of insulin therapy, we found that the most important barriers affecting the patient’s decision to start therapy were related to the impact of treatment on social life and misperceptions about the risks of insulin." (PMID 34712538, 2021). "The treatment for hypoglycemia strives to attenuate the insulin peak postprandially and might probably be the same as for hypokalemia, since supplying extra potassium will probably for most cases be of no or little effect in the acute phase of this physiological phenomenon." (PMID 33783679, 2021). "However, there is still much that is unknown about insulin, especially in hyperinsulinemia, hypoglycemia, and insulin-signaling targeted therapies." (PMID 34203830, 2021). "In conclusion, this large, prospective, observational study demonstrated that switching from NPH insulin to Gla-300 resulted in a significant improvement in HbA1c, with only a moderate increase in insulin dose, a decreased risk of hypoglycaemia, and no increase in body weight." (PMID 32337298, 2020). "Furthermore, our results suggest that Esp may act as a fine controller of insulin sensitivity in mice, offering protection from severe hypoglycaemia and dyslipidaemia." (PMID 33092598, 2020).
Hypoglycemia (continued). "In some cases, i.e., recipients of a kidney graft or patients affected by recurrent and severe hypoglycemia, islet transplantation is an option, allowing partial recovery of endogenous insulin secretion and, in most cases, transitory independence from exogenous insulin administration." (PMID 33019671, 2020). "Clinicians treating HCV-infected diabetics with DAAs should be aware that glycemia will probably improve and that hypoglycemia might occur, particularly if the patient is receiving insulin, a sulfonylurea, or a meglitinide, requiring careful blood glucose monitoring at home and in the clinic." (PMID 32395351, 2020). "Hypoglycemia, weight gain, and injection site reactions are well-known possible complications of insulin therapy, which might interfere with a patient's willingness to start or continue insulin therapy or long-term adherence to insulin therapy." (PMID 32982980, 2020). "The use of a p-insulin cut-off of 10.6–12.3 pmol/L during a diagnostic hypoglycemia test may establish the diagnosis of CHI without further diagnostic testing." (PMID 33679602, 2020). "Moreover, a study conducted subsequently on young people with T1D reported that HCL insulin delivery was safe both during and after physical activity maintaining glucose values mostly within the target range without an increased risk of hypoglycemia." (PMID 33153229, 2020). "It was expected that insulin or insulin-secreting drugs, which could cause hypoglycemia and thus AF, would have been prescribed to metformin non-users for the purpose of glycemic control in the subsequent years of follow-up." (PMID 33693008, 2020). "With such a large proportion of Swedish dementia patients being treated with insulin, we believe periodical continuous glucose monitoring are important especially in patients with advanced dementia or living alone, as cognitive decline increases the probability of hypoglycemia and vice versa." (PMID 32741836, 2020). "However, in this study, walking speed was still a determinant of MCI, and was not related to hypoglycemia, even after adjusting the use of SU or insulin, which had a risk of hypoglycemia." (PMID 32640726, 2020). "Insulin incremented the risk by 98–99%, and the use of non-insulin anti-DM drugs at risk for hypoglycaemia, by 90%, compared to non-insulin anti-DM drugs not at risk for hypoglycaemia." (PMID 32429960, 2020). "Interestingly, during insulin-induced hypoglycemia in healthy humans, the cerebral metabolic rate of glucose consumption is decreased to a greater extent than the rate of oxygen utilization, suggesting the metabolism of an alternative carbon source in these conditions." (PMID 32214088, 2020). "Subjects treated with insulin for less than 5 years had an increased probability of not being susceptible to ED attendances for hypoglycaemia (OR = 1.82, 95% CI = 1.25–2.65) and a reduced event frequency (IRR = 0.62, 95% CI = 0.52–0.74), compared to those treated for 5 years or more." (PMID 32429960, 2020). "Insulin secretagogue therapy was not a risk factor for hypoglycemia regardless of cut-off value." (PMID 32151247, 2020). "Similarly, the analysis of CGM-derived GV could improve prediction of nocturnal hypoglycemia in elderly patients treated with insulin, and minimizing GV could achieve good glycemic control without hypoglycemia." (PMID 32622354, 2020). "Similarly, weight-corrected total daily insulin dose and total daily bolus dose were associated with hypoglycemia reduction on univariate analysis, whereas the type of insulin and the mean number of boluses per day were not." (PMID 32412858, 2020). "However, the patients in our study who developed hypoglycemia were already on insulin or a sulfonylurea, suggesting that hypoglycemia in these patients was not primarily caused by dapagliflozin." (PMID 32550088, 2020).
Hypoglycemia (continued). "There were no changes in endothelial function seen in this study at 24 hours; however, it was not possible technically to undertake the Endo-Pat at the time of hypoglycemia concomitantly with the insulin clamp, and changes at this time point may have been missed." (PMID 32179763, 2020). "Interestingly, insulin-induced hypoglycemia increases ARC POMC neuron activity." (PMID 33293550, 2020). "In addition to enabling rapid access to interstitial blood glucose (they provide a proxy but do not actually measure the blood glucose value), they can now be coupled to the insulin pump, making it possible to activate the system to stop the insulin pump during hypoglycemia or before it occurs." (PMID 33102403, 2020). "Furthermore, our results suggest that a postprandial glucagon excursion preceding insulin peak might increase glucose levels at nadir, thus preventing hypoglycemia." (PMID 33424773, 2020). "The combined therapy of GLP‐1 RAs with oral antihyperglycaemic medications (OAMs) or insulin has been increasingly accepted in the treatment of T2DM because this combination not only improves glycaemic control but also avoids weight gain and an increased risk of hypoglycaemia." (PMID 32704576, 2020). "Studies of gain of function mutations or insulin infusion also did not result in elevated body fat, but this could be because developing hypoglycemia produces confounding effects on the metabolic rate and food intake." (PMID 32029228, 2020). "Furthermore, it is not possible to manipulate fetal insulin in isolation in vivo as this will subsequently cause fetal hypoglycaemia, which is not representative of the hyperglycaemic/hyperinsulinaemic environment of an obese pregnancy." (PMID 32919096, 2020). "In addition, the feasibility of whether the proposed metric can be used in insulin pump to achieve the insulin suspension before hypoglycemia at different prediction horizons needs to be further investigated." (PMID 33204733, 2020). "Therefore, future works will focus on the analysis of larger datasets, more representative of the overall T1D population, including a larger representation of hypoglycemia unawareness, subjects under different insulin regimens and subjects with larger incidence of hypoglycemia." (PMID 33097760, 2020). "We could not demonstrate that oral hypoglycemic agents or regular insulin use were associated with a higher risk of hypoglycemia." (PMID 33328554, 2020). "Thus, patients switching to V-Go from a variety of therapies at baseline experienced reductions in A1C while using less insulin, with a reduction in clinically relevant hypoglycemia, indicating the potential benefit of V-Go in optimizing and simplifying T2D care." (PMID 33202616, 2020). "We found that daily insulin dose has a slightly protective effect on the development of significant hypoglycemia, which could be related to the duration of therapy, use of the continuous glucose sensor, and the patient's care measures with higher doses of insulin." (PMID 32832557, 2020). "If analog insulin was shown to reduce the risk of life‐threatening hypoglycaemia, then the ethical question would not be whether to provide this insulin in low‐income countries, but how to make it affordable." (PMID 32704558, 2020). "Therefore, further insulin administration may not be recommended in patients who failed to achieve biochemical hypoglycemia but developed manifestations due to hypoglycemia from the initial insulin administration." (PMID 32187262, 2020). "Therefore, we speculated that the HFD-induced early fasting hypoglycemia is mainly due to excessive insulin as a response to the HFD." (PMID 32867177, 2020). "In this pooled analysis of the three GetGoal trials, addition of lixisenatide to basal insulin improved HbA1c and reduced postprandial glucose, regardless of baseline fasting plasma glucose, with no increased risk of symptomatic hypoglycemia while mitigating weight gain in patients with T2D." (PMID 31956422, 2020).
Hypoglycemia (continued). "Therefore, a possible effective solution for the prevention of profound hypoglycemia could be the combination of basal insulin attenuation algorithms with algorithms for the suggestion of preventive hypotreatments in presence of elevated hypoglycemia risk." (PMID 30922295, 2019). "Finally, proactively modifying insulin regimens led to effective therapy with minimal hypoglycemia." (PMID 31866948, 2019). "However, insulin therapy may induce important side effects, such as hypoglycemia, weight gain and cancer." (PMID 31156453, 2019). "In contrast to hypoglycemia incidence, basal insulin use was not an effect modifier for BB associated mortality though effect estimates were unstable and definitive conclusions could not be drawn." (PMID 31775749, 2019). "Interestingly, mice lacking vGlut2 in the VMH lack the ability to counteract hypoglycemia caused by insulin administration." (PMID 31572115, 2019). "Consequently, children and adolescents with IAH may experience fear of developing hypoglycemia, which may affect their adherence to insulin regimens and hence the achievement of a good glycemic control." (PMID 31651281, 2019). "Maintenance of weight loss and improved beta-cell function is important for postoperative glycemic control in patients with preoperative T2D, while the increased insulin secretion in response to glucose may explain postprandial hypoglycemia in NGT subjects after RYGB." (PMID 31641146, 2019). "The hypercortisolic state tends to be mild in patients with depression and a positive cortisol response to insulin-induced hypoglycemia, an attenuated ACTH response to the CRH test, and a negative ACTH response to the desmopressin test can be observed, although a wide overlap may exist." (PMID 31726770, 2019). "In a non-randomised prospective study of 605 inpatients receiving parenteral nutrition, intravenous insulin (infusion therapy or added to parenteral nutrition bag) was associated with a greater risk of hypoglycaemia compared with subcutaneous or no insulin therapy." (PMID 30935872, 2019). "Three episodes of severe hypoglycemia per treatment arm were reported (2.2% per arm) over the 44 weeks, three of which were considered serious adverse events (one in a subject using the patch and two in subjects using the pen) and related to intensifying insulin therapy." (PMID 31025878, 2019). "Just recently, acute insulin administration in mice was shown to induce both, hypothalamic AgRP expression and microglia activation suggesting a role for microglial cells in close vicinity to orexigenic neurons in facilitating the release of hunger signals to counteract hypoglycemia." (PMID 31572115, 2019). "Moreover, hypoglycemia is a frequent side effect of therapeutic treatment with insulin, sulfonylureas or glinides, while other treatments (metformin, acarbose, thiazolidinediones, GLP-1 receptor agonists, and DPP-4 inhibitors) are capable of reducing hyperglycemia without inducing hypoglycemia." (PMID 31366085, 2019). "Additionally, patients at risk of hypoglycemia in the absence of insulin, including those with acute alcohol intoxication or poor nutritional status, must be vigilantly monitored while in the ED." (PMID 31539342, 2019). "Mothers receiving metformin had a lower incidence of maternal hypoglycemia (RR, 0.28; 95% CI, 0.10 to 0.75; P = 0.05), gestational hypertension (RR, 0.56; 95% CI, 0.36 to 0.87; P < 0.01), and induction of labor (RR, 0.85; 95% CI, 0.74 to 0.99; P < 0.05) than those in the insulin group." (PMID 31781670, 2019). "Additionally, patients at risk of hypoglycemia in the absence of insulin, including those with alcohol intoxication or poor nutritional status, should be monitored closely in the ED." (PMID 31539342, 2019).